LAMB4 (laminin subunit beta 4)
Description:
Binding to cells via a high affinity receptor, laminin is thought to mediate the attachment, migration and organization of cells into tissues during embryonic development by interacting with other extracellular matrix components.
Tractability: Antibody: UniProt places it where antibodies can reach, with medium confidence; UniProt predicts a signal peptide or a membrane-spanning region; its Gene Ontology location is reachable by antibodies, with medium confidence. Other modalities: an approved drug acts on it.
Gene: Protein-coding gene on chromosome 7 (108,023,548 to 108,130,361, reverse strand). Ensembl gene ENSG00000091128.
Subcellular location: Secreted, extracellular space, extracellular matrix, basement membrane
Gene Ontology:
Molecular function: extracellular matrix structural constituent
Biological process: substrate adhesion-dependent cell spreading
Cellular component: basement membrane; laminin-11 complex; laminin-14 complex; laminin-15 complex; laminin-3 complex; laminin-4 complex; laminin-522 complex; laminin-7 complex; laminin-9 complex
Genetic constraint (gnomAD): Loss-of-function variants: 146 observed, 153.64 expected, observed/expected ratio (o/e) 0.95, 90% interval 0.83 to 1.09. The upper end of that interval is the gene's LOEUF score, 1.09, which puts it in group 4 of 6, group 1 being the genes least tolerant of losing a copy. Missense variants: 1,736 observed, 1,887.1 expected, observed/expected ratio (o/e) 0.92, 90% interval 0.88 to 0.96. Synonymous variants: 624 observed, 682.68 expected, observed/expected ratio (o/e) 0.91, 90% interval 0.86 to 0.98.
Homologues: Orthologues: chimpanzee LAMB4 (99% identical), macaque LAMB4 (96% identical), dog LAMB4 (77% identical), pig LAMB4 (74% identical), tropical clawed frog lamb4 (50% identical), zebrafish lamb4 (44% identical). Paralogues in human: LAMB1 (41% identical), LAMB2 (39% identical), LAMA5 (23% identical), LAMA1 (22% identical), LAMA2 (21% identical), LAMB3 (21% identical), LAMA3 (21% identical), LAMC3 (20% identical), LAMC1 (20% identical), USH2A (19% identical), HSPG2 (17% identical), AGRN (15% identical), and 15 more.
Diseases named in the same sentence as LAMB4 in open-access papers:
LAMB4 is named in the same sentence as 20 diseases in open-access papers, as found by Europe PMC text mining. Sharing a sentence is not in itself a finding about the gene and the disease. The quoted sentences say what the papers report.
colorectal cancer (5 papers, 2022 to 2025). A primary or metastatic malignant neoplasm that affects the colon or rectum. "Germline truncating variants in LAMB4 have been detected in individuals with colorectal cancer, with somatic second hits confirming the biallelic inactivation characteristic of tumor suppressor genes." (PMID 40868176, 2025). "Frameshift mutations in LAMB4 and related laminin genes have been observed in gastric and colorectal cancers." (PMID 40868176, 2025). "LAMB4 is somatically mutated and expressionally altered in gastric and colorectal cancers." (PMID 35903675, 2022). "Previous research has shown that gene mutations in certain patients with gastric cancer, colorectal cancer, and pancreatic cancer can cause a decrease or absence of laminin β4 (LAMB4) expression." (PMID 37686118, 2023).
diverticulitis (2 papers, 2018 to 2024). An infection that develops in the diverticula of the intestinal tract. "A rare SNP encoding a D435N substitution in LAMB4 has also been described in diverticulitis and is known to play a role in intestinal barrier function." (PMID 38831715, 2024).
glioma (2 papers, 2017 to 2023). A benign or malignant brain and spinal cord tumor that arises from glial cells (astrocytes, oligodendrocytes, ependymal cells). "We subsequently found that ADAMTS20 and FREM3 were interrelated lower risk of glioma using Cox regression analysis, whereas LAMB4, MMP1, and MMP7 showed high risk of glioma." (PMID 37335645, 2023). "This study demonstrated that high-risk genes (LAMB4, MMP1, MMP7) promote glioma progression and negatively correlate with patient prognosis." (PMID 37335645, 2023). "For the sake of clarifying the expression of BMGs in glioma, this study screened 9 BMGs that were upregulated in glioma (FBN2, FREM3, Lamb4, MEP1A, MMP1, MMP7, OPTC, EVA1A, and ADAMTS20) from TCGA -GTEX expression matrix." (PMID 37335645, 2023).
dilated cardiomyopathy (1 paper, 2020). Cardiomyopathy which is characterized by dilation and contractile dysfunction of the left and right ventricles. "Coding exons of LAMB1, LAMB4 and PIK3CG were screened in dilated cardiomyopathy." (PMID 33041871, 2020).
Familial dysautonomia (1 paper, 2024). "To assess if LAMB4 has clinical relevance, we studied the genetic disorder Familial Dysautonomia (FD), which specifically affects the peripheral nervous system." (PMID 39605577, 2024).
Hyperglycemia (1 paper, 2023). An increased concentration of glucose in the blood. "The laminins LAMA2 and LAMB4 are targets in the treatment of ocriplasmin vitreomacular adhesion, whereas the amylases AMY2A and MGAM are targeted by acarbose, voglibose and miglitol for the improvement of postprandial hyperglycemia." (PMID 37684227, 2023).
squamous cell carcinoma (1 paper, 2022). A carcinoma arising from squamous epithelial cells. "Consistent with these previous studies, our analysis of LAMB3 and LAMB4 from the TCGA-HNSC dataset indicated that both LAMB3 and LAMB4 could serve as prognostic markers for squamous cell carcinoma." (PMID 36081907, 2022).
cancer (5 papers, 2018 to 2025). A tumor composed of atypical neoplastic, often pleomorphic cells that invade other tissues. "A significant proportion of these cancers with LAMB4 mutations also exhibited loss of LAMB4 protein expression." (PMID 40868176, 2025). "LAMB4 is implicated in tissue development and cell migration, and has been associated with different types of cancer." (PMID 33256133, 2020). "In contrast to LAMB3, the role of LAMB4 in cancer has not been intensively investigated." (PMID 36081907, 2022).
tumor (5 papers, 2022 to 2025). "However, LAMA1 was not statistically significantly different between groups, while LAMC3 and LAMB4 showed slight decreases in expression in tumour samples." (PMID 37779898, 2023). "Therefore, as a potential tumor suppressor gene, silencing LAMB4 promoted the proliferation and migration of HNSCC cell lines." (PMID 36081907, 2022).
diseases of the peripheral nervous system (1 paper, 2024). "LAMB4 downregulation is linked to diseases of the peripheral nervous system (peripheral neuropathies)." (PMID 39605577, 2024).
infection (1 paper, 2021). The state of being infected such as from the introduction of a foreign agent such as serum, vaccine, antigenic substance or organism. "As well as secreting collagen, they have a 14-fold increase in RNA expression of laminin β4 (LAMB4) at 48 h post infection." (PMID 34681953, 2021).
peripheral neuropathy (1 paper, 2024). A disorder affecting the peripheral nervous system. "Patients with severe symptoms of the peripheral neuropathy FD harbor mutations in the LAMB4 gene." (PMID 39605577, 2024).
LAMB4 also shares sentences with these, for which no sentence is quoted: gastric cancer (2 papers); cardiovascular diseases (1); chronic obstructive pulmonary disease (1); dysautonomia (1); end-stage renal disease (1); genetic disorder (1); head and neck squamous cell carcinoma (1); pancreatic cancer (1).